PI3 (peptidase inhibitor 3)
Diseases named in the same sentence as PI3 in open-access papers (continued):
Sharing a sentence is not in itself a finding about the gene and the disease.
viral infections (7 papers, 2011 to 2025). "IFI44L and PI3 transcript levels are robust classifiers to discriminate bacterial from viral infection in UC-OI, and measuring its levels appears to be predictive infection progression and treatment outcome in UC patients over time." (PMID 41050698, 2025). "We screened for differentially expressed genes associated with bacterial or viral infections (IFI44L, PI3 and ITGB2) and compared the expression levels of the genes in different infection subgroups." (PMID 41050698, 2025). "PI3 showed significant changes in virus infection, with a logFC from 2.34 to 2.48 in three datasets, indicating upregulation, and the adjusted P-values were all smaller than 0.05, reflecting its strong robustness." (PMID 41050698, 2025). "Although severe viral infection may cause IFI44L downregulation, the two-transcript model incorporating PI3 effectively resolves this confounding factor to ensure diagnostic accuracy." (PMID 41050698, 2025). "Furthermore, IFI44 and PI3 remained significantly different between UC patients with bacterial and viral infections in multivariable analysis." (PMID 41050698, 2025). "Pi3-akt signaling has been shown to play an important role in viral infections." (PMID 29744032, 2018). "There are many bovine viral diseases in Ireland, including bovine viral diarrhoea (BVD) and several viral infections associated with the respiratory system (infectious bovine rhinotracheitis [IBR], bovine parainfluenza-3 [PI-3] and bovine viral syncytial virus [BRSV])." (PMID 21777492, 2011). "Our five genes included three genes overexpressed in bacterial infections (LCN2, PI3, and SLPI) and two overexpressed in viral infections (IFI27 and IFIT2)." (PMID 40843077, 2025). "Actually, we identified that LCN2, PI3, and SLPI were up-regulated in bacterial infections, and IFI27 and IFIT2 were up-regulated in viral infections in the study, which may be helpful in assisting with the diagnosis of B/V co-infection in children." (PMID 40843077, 2025). "Differential expressed genes analysis of IFI44L, PI3 and ITGB2 in bacterial and viral infections." (PMID 41050698, 2025). "There was no serological evidence for PI3 and IBR, the main viral infections of Iranian livestock, and there was just one Indian gazelle positive for BHV 1 using PCR." (PMID 27997620, 2016). "Its mechanism of action is, however, poorly understood and down-regulation of PI3 has been reported previously in patients with acute respiratory distress syndrome (ARDS), but not in studies of viral infections." (PMID 26070066, 2015).
asthma (6 papers, 2018 to 2025). "Regarding PI3, which encodes trappin-2 (precursor of elafin), an antimicrobial peptide and protease inhibitor with anti-inflammatory effects, its role in asthma is less explored." (PMID 41154593, 2025). "PI3 has also been linked to lung tissue repair and is a candidate biomarker for lung diseases including acute respiratory lung disease and asthma, as well as modulator of inflammation through the inhibition of neutrophil derived elastases." (PMID 33210602, 2020). "Previously, we defined CHI3L1 and PI3 as genes related with asthma and severity by analysis of differential gene expression." (PMID 41154593, 2025). "In this study, we aim to further validate the utility of CHI3L1 and PI3 expression as asthma biomarkers and explore the role of DNA methylation as an epigenetic modulator involved in their regulation." (PMID 41154593, 2025). "Our findings support previous evidence indicating altered expression of CHI3L1 and PI3 in asthma, particularly at the gene level." (PMID 41154593, 2025). "Previously reported overexpressed (IL-10, MSR1, PHLDA1, SERPINB2, and CD86) and underexpressed genes (CHI3L1, CPA3, IL-8, and PI3) in severe asthma were analyzed by RT-qPCR in peripheral blood mononuclear cells (PBMCs)." (PMID 37445432, 2023). "In conclusion, CHI3L1 and PI3 represent potential asthma biomarkers, whose regulation may be partially influenced by DNA methylation, a mechanism more pronounced in asthmatic patients than in healthy subjects." (PMID 41154593, 2025). "Targets of these miRNAs were significantly enriched in a number of known asthma- and COPD-related pathways, including PI3-AKT and MAPK signaling." (PMID 35447890, 2022). "When two biomarkers were combined, the combinations of CHI3L1 + POSTN, IL10 + POSTN, IL-8 + PI3, and SERPINB2 + POSTN were good to discriminate severe from moderate–mild asthma, and of smaller importance was the grouping of IL-8 + POSTN." (PMID 29977241, 2018). "In conclusion, our results support CHI3L1 and PI3 as gene biomarkers for allergic and nonallergic asthma." (PMID 41154593, 2025). "In a recent work, new gene and protein biomarkers CHI3L1, IL-8, IL-10, MSR1, PHLDA1, PI3, and SERPINB2, were proposed to discriminate healthy control subjects from nonallergic asthmatic patients (T2-low) and to measure asthma severity." (PMID 31143187, 2019).
Insulin resistance (6 papers, 2019 to 2026). Increased resistance towards insulin, that is, diminished effectiveness of insulin in reducing blood glucose levels. "Insulin resistance and IGF1 are also thought to play an important role in ABCD‐linked PCa risk via PI3/AKT, FOXO3A, and BIM signaling, causing angiogenesis, cell survival, growth, and invasion." (PMID 41450167, 2026). "It other studies, it was demonstrated that pancreatic cancer-derived exosomes induce insulin resistance in recipient cells through the PI3/Akt/FOXO1 signaling pathway, highlighting their role in altering cellular function." (PMID 40699634, 2025). "The characteristics of oxidative stress and the impaired PI3 pathway may favor the insulin resistance in rats and patients with hypertension." (PMID 30906419, 2019). "In addition to the PI3/Akt, the FA pathway can act against insulin resistance." (PMID 37123284, 2023). "The failure of dasatinib in palmitic acid-induced insulin-resistant cells could perhaps allude to the lack of functional PI3/AKT pathway in this model, as this is a well-established in vitro insulin resistance model." (PMID 41155560, 2025).
acute respiratory distress syndrome (5 papers, 2015 to 2025). Progressive and life-threatening pulmonary distress in the absence of an underlying pulmonary condition, usually following major trauma or surgery. "Notably, PI3 was found to be suppressed in the acute phase of acute respiratory distress syndrome and to play a critical role in its progression." (PMID 39688402, 2025). "At eight RET exposures, SpO2 decreases, and the hypermethylation of PI3’s cg19931348 may inhibit its expression; PI3 is significantly downregulated in patients with acute respiratory distress syndrome." (PMID 39684363, 2024).
atherosclerosis (5 papers, 2017 to 2025). A disease characterized by the build-up of fatty material and calcium deposition in the arterial wall resulting in partial or complete occlusion of the arterial lumen. "It has been found that AD patients have increased levels of markers of atherosclerosis including fractalkine/CX3CL1, CCL8, M-CSF, and HGF, as well as increased levels of mediators of atherosclerosis such as E-selectin or PI3/elafin, CCL17, and IL-16, which are proportional to SCORAD." (PMID 34551806, 2021). "However, inflammatory mediators involved in atherosclerosis development (E-selectin, CCL7, IL16, PI3/elafin) were significantly correlated with AD severity/SCORAD, but not with BMI, strongly suggesting the contribution of cutaneous disease to cardiovascular morbidity." (PMID 28821884, 2017).
colon carcinoma (5 papers, 2014 to 2023). "Our mining of a microarray dataset of serrated colon carcinoma specimens determined that peptidase inhibitor 3 (PI3), vanin 1 (VNN1) and annexin 10 (ANXA10) are more highly expressed in such cancers as compared to conventional colon carcinomas." (PMID 24533081, 2014). "Overexpression of AQP8 has been linked with reduced migration and invasion through inhibition of PI3/Akt in colon cancer, and pathologies such as epithelial ovarian, cervical, colorectal, and liver cancers also have been associated with altered AQP8 expression." (PMID 37760476, 2023).
diabetes (5 papers, 2017 to 2025). "In type 2 diabetes mellitus, because of increased insulin resistance and physiological PI-3/Akt pathway deficiency, the MAPK pathway predominates, with a proatherogenic effect." (PMID 38921685, 2024). "On the contrary in the setting of diabetes mellitus, high glucose was shown to induce PI3-Akt and TGF-β-1 mediated activation of Akt contributing to epithelial mesenchymal transformation." (PMID 40313745, 2025). "Researchers have also shown that PI3/Akt phosphorylation is down regulated in diabetes." (PMID 35054496, 2022). "However, differences in PI3/Akt signaling do not seem to explain the disparate findings related to myocardial susceptibility to IR injury in different animal models of diabetes." (PMID 31151453, 2019).
glioblastoma (5 papers, 2015 to 2025). The most malignant astrocytic tumor (WHO grade IV). "Previous studies showed that survivin is regulated by TGFβ through the ERK1/2 or PI3/AKT pathways in other cancer types including glioblastoma." (PMID 29212257, 2017). "As for its biological function in tumorigenesis, transcripts of PI3 are extremely abundant in glioblastoma patient samples and significantly correlated with dismal survival." (PMID 25970782, 2015). "D1 peptide not only inhibited the Src and PI3/AKT pathways, but also significantly suppressed the induction of MT1-MMP in glioblastoma cells." (PMID 30318506, 2018). "In glioblastoma CSCs, NR1D2 regulates proliferation through the AXL/PI3/Akt signalling pathways." (PMID 40564218, 2025).
lung carcinoma (5 papers, 2014 to 2023). "In order to improve the clinical translational benefit of microRNAs in lung cancer research, we have generalized and summarized the way of action of microRNAs linked with the PI3/AKT signaling pathway in this review through literature search and data analysis." (PMID 38169723, 2023). "Also, natural products (NP) activate apoptotic pathways in lung cancer cell including p‐JNK, Akt/mTOR, PI3/ AKT\ and Bax, Bcl2, but suppressed AXL phosphorylation." (PMID 37697969, 2023). "As PI3/AKT/GSK axis being a prominent pathway inducing Nrf2 activation and as Akt inhibitor, MK2206 has been shown effective in reducing Nrf2 accumulation in A549 lung carcinoma cells, we tested the effect of Nrf2 inhibition with MK2206 in AML cells." (PMID 28505160, 2017).
pancreatic cancer (5 papers, 2015 to 2025). "This suggests that Ir influences EMT suppression of ovarian and pancreatic cancer cells through the PI3/AKT pathway by inhibiting AKT phosphorylation." (PMID 37239973, 2023). "In addition, pancreatic cancer cell mobility was suppressed by baicalein through the downregulation of the PI3/Akt and MEK/ERK signaling pathways." (PMID 35056061, 2021). "Atorvastatin was also shown to influence the cellular activities of components of the PI3/AKT signaling molecules such as AKT, P2X7, pERK, RhoA, cyclin D1, and β-catenin to inhibit proliferation and induce apoptosis in pancreatic cancer cells." (PMID 26229958, 2015).
prostate carcinoma (5 papers, 2013 to 2025). A carcinoma that arises from epithelial cells of the prostate gland. "Since PI3-AKT signaling has been shown to have pro-survival and pro-proliferative roles in prostate cancer, something we confirmed by using the PI3 inhibitor LY294002, we hypothesized that Peptide A-8R will interfere with the sGCα1 positive effect on AKT." (PMID 23724033, 2013).
colorectal cancer (4 papers, 2015 to 2024). A primary or metastatic malignant neoplasm that affects the colon or rectum. "PLXNDI, in conjugation with SEMA3E, enhances the Epithelial-Mesenchymal Transition by activating the PI3/Akt signaling pathway in colorectal cancer and through SEMA3E in endometrioid cancer." (PMID 38627856, 2024).
hepatocellular carcinoma (4 papers, 2020 to 2024). A malignant tumor that arises from hepatocytes. "It is suggested that the combined action of 6-shogaol and curcumin against hepatocellular carcinoma may be related to the inhibition of PI3/AKT and MAPK signalling pathways, upregulation of Bax and Caspase-3 proteins, and downregulation of Bcl-2, Cyclin-B, and CDK-1 proteins." (PMID 39224778, 2024). "Taken together, ZNF191 may function through upregulating DNMT1, regulating DNA methylation of genes involved in the PI3‐AKT pathway and activating the signaling to promote hepatoma cell proliferation." (PMID 35092191, 2022).
Hyperglycemia (4 papers, 2013 to 2022). An increased concentration of glucose in the blood. "Genistein is capable of modulating hyperglycemia by activating the hepatic IRβ/PI3/AKT signaling pathway, increasing the phosphorylation of hepatic Foxo1/GSK3β and improving glucose metabolism of liver." (PMID 36570152, 2022). "In response to hyperglycemia, pancreatic β-cells secrete insulin, which binds to its receptor, activates PI3/Akt signaling, induces the translocation of glucose transporter 4 to the plasma membrane, and promotes glucose uptake in various cells, such as skeletal muscle cells." (PMID 36145139, 2022).
neuroblastoma (4 papers, 2016 to 2025). Neuroblastoma (NB) is the most common solid, extracranial childhood tumor. "Strong phosphorylation of the S6 ribosomal protein (a target of mTOR) was also observed in neuroblastoma samples; therefore, the PI3/Akt/mTOR pathway affects several pathways or proteins promoting a more aggressive cancer cell phenotype." (PMID 40104501, 2025). "In neuroblastoma, the PI3/Akt/mTOR pathway has been found to affect multiple pathways/proteins to enhance the neuroblastoma phenotype, such as stabilizing MYCN, which in turn facilitates processes associated with malignancy like proliferation, angiogenesis, and metabolic reprogramming." (PMID 39319058, 2024).
cardiac hypertrophy (3 papers, 2016 to 2023). "Atrogin-1 was shown to inhibit cardiac hypertrophy via targeting of calcineurin/nucleus factor of activated T (NFAT) and phosphatidylinositol-3 (PI-3)/Akt/Foxo signalling pathways." (PMID 36969608, 2023). "Other studies reported that allicin protected cardiac function and prevented the development of cardiac hypertrophy through ROS-dependent mechanism involving multiple intracellular signaling (ERK1/2, JNK1/2 and PI3/Akt/GSK3β signaling pathways)." (PMID 27990229, 2016). "It has been known that pAKT T308 was upregulated by TAC via the activated PI3/PDK1 signaling, resulting in the activation of mTORC1 substrates, which leads to cardiac hypertrophy; however, the change and the role of pAKT S473 in the TAC‐induced hypertrophy remain controversial." (PMID 28799247, 2017).
Cerebral ischemia (3 papers, 2015 to 2023). Restriction of arterial blood supply to the brain associated with insufficient oxygenation to support the metabolic requirements of the tissue. "We speculate that Dl-3-n-butylphthalide has a neuroprotective effect on focal cerebral ischemia/reperfusion, which may be mediated through ferroptosis-dependent SLC7A11/GSH/GPX4 signal pathway and PDGFRβ/PI3/Akt signal pathway." (PMID 36909944, 2023).
endometrial cancer (3 papers, 2019 to 2025). Primary or metastatic malignant neoplasm involving the endometrium (mucous membrane that lines the endometrial cavity). "The pathways included extracellular matrix-receptor interaction, leukocyte trans-endothelial migration, endometrial cancer, bacterial invasion of epithelial cells, PI3-AKT signaling, mTor signaling, protein processing in the endoplasmic reticulum, and focal adhesion." (PMID 30777008, 2019).
lymphoma (3 papers, 2013 to 2023). A malignant (clonal) proliferation of B- lymphocytes or T- lymphocytes which involves the lymph nodes, bone marrow and/or extranodal sites. "The activation of GLI1 transcription factor by ALK was reported in a lymphoma cell line and was ascribed to signaling through PI3/Akt." (PMID 24163262, 2013). "It has been reported that ALK induces GLI1 mRNA expression via PI3/Akt in a lymphoma cell line." (PMID 24163262, 2013).
pneumonia (3 papers, 2011 to 2024). An acute, acute and chronic, or chronic inflammation focally or diffusely affecting the lung parenchyma, caused by an infection in one or both of the lungs (by bacteria, viruses, fungi, or mycoplasma.). "and viruses (BRSV, PI3) have been implicated as primary or secondary pathogens in enzootic and epizootic pneumonia, and we associate these organisms with pneumonic disease because they can be detected in sick and dead animals." (PMID 21284886, 2011).
serous ovarian carcinoma (3 papers, 2012 to 2023). "More recently, another study using tissue microarray composed of late stage, high-grade serous ovarian carcinomas correlated PI3 expression with poor overall survival." (PMID 22355333, 2012).
Alzheimer disease (2 papers, 2022 to 2024). A progressive, neurodegenerative disease characterized by loss of function and death of nerve cells in several areas of the brain leading to loss of cognitive function such as memory and language. "Current research has confirmed that downregulating LRIG3 in an Alzheimer’s disease rat model can inhibit oxidative stress damage and inflammatory injury by modulating the PI3/Akt pathway." (PMID 38982427, 2024).
autism (2 papers, 2021 to 2022). Persistent deficits in social interaction and communication and interaction as well as a markedly restricted repertoire of activity and interest as well as repetitive patterns of behavior. "The PI3/AKT/mTOR pathway and its regulation by the protein known as the phosphatase and tensin homolog (PTEN), have long been known to be important players in the pathogenesis of autism." (PMID 33735311, 2021).
Autoimmunity (2 papers, 2021 to 2024). The occurrence of an immune reaction against the organism's own cells or tissues. "FGF family uses Ras/MAPK, PI3, and PLCγ pathways, through which it helps for neuroprotection, cell survival, and neural differentiation during embryonic development, it is also linked with epileptogenesis, mood disorders and autoimmunity in the brain." (PMID 33833673, 2021). "Aberrant splicing might result in elevated levels of defective PI3 protein, which fails to adequately counteract the detrimental effects of cytokines, thus triggering tissue damage associated with autoimmunity." (PMID 38255930, 2024).
bladder cancer (2 papers, 2019 to 2024). "Expression of MTHFD2 in bladder cancer tissues correlates with PD‐L1 expression, which was proposed to be mediated by the PI3/AKT and JAK/STAT pathways." (PMID 39540204, 2024). "Besides, the abundance of SCD is much more higher than PI3 in bladder cancer." (PMID 30592142, 2019). "The Lee bladder dataset is considered because it contains gene expression levels for both SCD and PI3, survival status, follow‐up time, TNM stage and progression status for patients with bladder cancer." (PMID 30592142, 2019).
cervical cancer (2 papers, 2020 to 2025). A primary or metastatic malignant neoplasm involving the cervix. "Emerging evidence suggests that PI3 concentration and subcellular localization may serve as potential biomarkers for assessing cervical cancer progression." (PMID 40534859, 2025). "The PI3/AKT inhibitor LY294002 was used to block AKT’s endogenous activity to assess the relationship between USP18 and AKT in cervical cancer cells." (PMID 32770981, 2020).